SPHK1 (sphingosine kinase 1)
Diseases named in the same sentence as SPHK1 in open-access papers (continued):
Sharing a sentence is not in itself a finding about the gene and the disease.
cancer (continued). "Currently, many cancer studies demonstrate that SPHK1/S1PRs inhibitors, such as MP-A08, SKI-I, SKI-II, FTY720, LCL146, LCL351, SLP7111228 and B5354c, are able to suppress cancer cell proliferation or apoptosis induction in breast cancer, bladder cancer, leukemia cells, and PCa." (PMID 36009418, 2022). "SphK1 overexpression and activation could increase cellular S1P contents, thereby promoting cancer initiation and progression." (PMID 35115496, 2022). "Increased SPHK1 expression is related to poor prognosis in human cancers and may serve as a promising prognostic marker and therapeutic target for malignant patients." (PMID 35126792, 2022). "What is emerging is that, as we learn more about the role of individual SphK1 isoform functions, the understanding of SphK1 isoform expression in cancer may become an important factor in personalized designer anti-SphK drug therapy." (PMID 36532885, 2022). "Furthermore, it has been suggested that S1P released by SPHK1 activity promotes EMT in cancer by inhibiting the Snail-matrix metalloproteinases and remodeling the glycocalyx signaling pathway." (PMID 35126792, 2022). "At this stage, we have no direct evidence to suggest the association of the SphK1 isoform with chemoresistance or hormone resistance in cancer patients." (PMID 36532885, 2022). "We demonstrated that SphK1a is expressed in all cancer cells and tissue types tested, and expression of the 1b-isoform is cell- and tissue-specific; the human prostate, breast, and lung expressed both SphK1 isoforms; however, liver tissues (cancer and adjacent) only expressed the SphK1a isoform." (PMID 36532885, 2022). "In addition, a correlation analysis was performed between SPHK1 and immune checkpoint molecule expression levels in 33 human cancers." (PMID 36050478, 2022). "Thus, SphK1-generated S1P is a lipid metabolite that is critical for cancer cell survival under conditions that promote endoplasmic reticulum stress." (PMID 36358599, 2022). "There is a strong suggestion that imbalances of SphK1 isoform abundance may play a crucial role in the pathophysiology of diverse diseases and may contribute to resistance to current anti‐cancer drug therapies." (PMID 35184376, 2022). "Novel evidence indicates that Sphk1/S1P may promote cancer cell transformation, epithelial-mesenchymal transition, and invasiveness." (PMID 33628783, 2021). "Therefore, the aim of this study was to investigate the role of SphK1 on autophagy, focal adhesion paxillin, and the metastatic capabilities of cancer cells in vitro and in vivo." (PMID 34268882, 2021). "Some have also shown that SPHK1 activity is responsible for the induction of inflammation and maintaining the Warburg effect and cell survival, which further enable the acquisition of cancer hallmarks in affected cells." (PMID 34820423, 2021). "To conclude, the concept that SPHK1 inhibition in combination with chemotherapeutic therapies might sensitize resistant cancer cells to currently inefficient regimens has emerged." (PMID 33660008, 2021). "Likewise, the down-regulation of SphK1 via targeted inhibition induces apoptosis and enhances the sensitivity of cancer cell lines towards chemo- and radiation therapy." (PMID 33920887, 2021). "In addition, an increasing number of studies have shown the potential therapeutic value of SPHK1, which provides new strategies for cancer treatment to improve the prognosis of cancer patients." (PMID 34869345, 2021). "Furthermore, the role of SphK1‐driven autophagy activation and its influence on focal adhesion paxillin and the metastatic capabilities of cancer cells were examined." (PMID 34268882, 2021). "The different localization of SphK1 and SphK2 determines the characteristics of mediating a variety of biological functions, such as the deposition of amyloid β-protein (Aβ) in AD and the pathogenesis of different cancers." (PMID 34737701, 2021).
cancer (continued). "We aim to offer new insights and inspire future studies looking further into the regulatory functions of SPHK1 in CSC-driven tumorigenesis, uncovering novel therapeutic avenues of using SPHK1-targeted therapy in the treatment of CSC-enriched refractory cancers." (PMID 34820423, 2021). "Importantly, ABC294640 is a structural analog of SKI-II, which was developed to be more selective for SPHK2 than for SPHK1, and is currently in clinical trials for cancer chemotherapy." (PMID 34033645, 2021). "Most importantly, SphK1 can serve as a promising marker of cancer prognosis." (PMID 34831211, 2021). "Moreover, several studies demonstrated that the interaction between epigenetics and SphK1 modified cancer initiation and progression." (PMID 34831211, 2021). "SphK1 inhibition, however, would lead to ceramide production that promotes cancer cell apoptosis." (PMID 33465049, 2021). "However, in many types of human cancers, SphK1 overexpression and/or over-activation would promote cancer cell growth and proliferation." (PMID 32203055, 2020). "There was a significantly enhanced expression of SPHK1 in cancer tissue compared to normal tissue." (PMID 32630814, 2020). "SphK1 inhibition is considered as an attractive strategy for cancer therapeutics." (PMID 32526899, 2020). "Discovery of more potent and selective SphK1 inhibitors could lead to the development of new therapy for the treatment of cancer and/or immune-mediated diseases." (PMID 32526899, 2020). "In addition, FTY720 inhibited the SphK1/S1P/S1PR1 axis and abrogated NF-κB/IL-6/STAT3 signaling, which reduced the severity of colitis and colitis-associated cancer." (PMID 32456134, 2020). "Out of the two, SPHK1 is the most common form involved in the cancer cell growth and survival." (PMID 32170160, 2020). "It’s reported that high expression level of SPHK1 promoted the development of tumor malignancy and significantly correlated with occurrence and poor prognosis of cancer patients, so we firstly analyzed the correlation between SPHK1 expression and the survival of CRC patients." (PMID 31723122, 2019). "As these target genes are critically involved in the proliferation and survival of cancer cells, alteration of these genes by SPHK1/2 could be responsible for anti-cancer activity." (PMID 31817453, 2019). "Furthermore, SphK1 plays important role in processes like angiogenesis, tumorigenesis and chemotherapy resistance which are crucial for metastasis and cancer progression." (PMID 31822735, 2019). "Sphingosine kinases (SPHK1/2) have recently become widely explored targets for cancer therapy." (PMID 31817453, 2019). "Due to the frequency with which hyperactivation of the RAS pathway occurs in cancer, constitutive phosphorylation and activation of SPHK1 in cancer is likely to be common, promoting drug resistance by not only depleting ceramide levels but also promoting pro-survival signalling." (PMID 30062053, 2018). "SphK1 is highly expressed in the tumor stroma of high grade serous ovarian cancer (HGSOC) and is required for the differentiation and tumor promoting function of cancer-associated fibroblasts (CAFs)." (PMID 29987226, 2018). "We found that EGFR levels were increased in the SphK1-overexpressing cancer cells." (PMID 29385066, 2018). "We propose this mechanism may be common to certain types of cancer cells and may partially explain the diverse effects on the cell cycle by SPHK1 blockage." (PMID 29643855, 2018). "Moreover, several cancer types demonstrated continuously increased levels of SphK1 expression, confirming selective requirement for the presence of this kinase in the maintenance of malignancy." (PMID 29385066, 2018). "This membrane translocation of SphK1 was defined as a critical determinant of cancer progression." (PMID 29385066, 2018). "Interestingly, this simplistic viewpoint has shifted and recent emerging functions of SphK1 and SphK2, relevant to the newly emerging SphK-targeting cancer therapies, will be discussed." (PMID 28415564, 2017).
cancer (continued). "Cancer patients overexpressing SphK1 tend to have poorer survival rates." (PMID 28415564, 2017). "Moreover, the reduction of Sphk1 restored cancer cells’ sensitization to chemotherapy and radiotherapy in vitro." (PMID 28991193, 2017). "Previous studies suggest that SphK1 appears to act as an oncogenic enzyme regulating various processes which is important in cancer progression and even shows physiological regulatory functions on antiapoptosis, transformation, proliferation, and survival of tumor cells." (PMID 29179493, 2017). "SphK1 mediates insulin-like growth factor binding protein-3 (IGFBP-3) growth factor signaling in breast cells, where overexpression of IGFBP-3 is associated with cancer progression." (PMID 28415564, 2017). "Hence, the term drugging the addict(s) (SphK1, SphK2 and S1PRs) has been the driving force for novel cancer drug design." (PMID 28415564, 2017). "Indeed, the dichotomy of the individual roles of SphK1 and SphK2 are even more blurred when it comes to more aggressive cancers or metastasis and treatments which target SphK1 and/or SphK2." (PMID 28869494, 2017). "Most importantly, the adverse effects of FTY720 are attributed to its phosphorylated isoform, FTY720-P, while the anti-cancer effects, exerted via interaction with targets, such as SET-PP2A and SphK1, have been specifically associated with the unphosphorylated form of FTY720." (PMID 28298211, 2017). "Thus, in hypoxic tumors, HIF-1α regulates many genes involved in cancer development and SPHK-1 regulates and stabilizes HIF-1α through the AKT/GSK-3β pathway." (PMID 28165392, 2017). "Interestingly, SphK1 has been found to have high expression in many types of cancer and inhibition of its activity subsequently leads to accumulation of ceramide in tumor cells." (PMID 28212569, 2017). "However, given the importance of SphK1 in malignancy, it is anticipated that new SphK1 targets will be discovered, especially for hard to treat cancers that overexpress SphK1." (PMID 28869494, 2017). "Determining the relative expression levels of each of theSphK1 isoforms may reveal novel roles for the two major SphK1 isoforms in cancer and other disease development and/or progression." (PMID 28415564, 2017). "The analogue of sphingosine, FTY720 (Fingolimod), is an Food and Drug Administration (FDA)-approved immunomodulator and has been shown effective in vitro and in vivo cancer models through functional antagonism of S1PR1 and inhibition Sphk1, suggesting a potential therapeutic role in cancer patients." (PMID 28991193, 2017). "In addition, GO analysis showed that SPHK1 enriched in multiple cancer-related processes including positive regulation of cell migration." (PMID 28231844, 2017). "As a consequence SphK1 demonstrated an increase in catalytic activity and bioactive S1P, proposing that the pro-cancer effect, or SphK1-oncogenic ‘inside-outside’ signalling, was reliant on both Ser225-specific phosphorylation and translocation to the membrane." (PMID 28415564, 2017). "On the other hand, the role of S1P in cancer progression was demonstrated by studies showing that activation of sphingosine kinase 1 and production of S1P inhibits apoptosis, allowing survival of cancer cells, and promotes angiogenesis, metastasis, and tumor growth." (PMID 28362332, 2017). "It is well known that SPHK-1 expression is related to cancer cell proliferation and progression." (PMID 28165392, 2017). "Interestingly, hSphK2 ablation using RNA interference technology was shown to be more efficacious in inducing cell death validating both SphK1 and SphK2 as targets for anti-cancer treatment." (PMID 28415564, 2017). "Similarly, the downregulation of SphK1 has proven able to induce apoptosis and confer sensitivity to chemo- or radiation therapy of cancer cell lines." (PMID 28878674, 2017). "The oncogenic role of Sphk1 has been explored in a range of cancers." (PMID 26956050, 2016).
cancer (continued). "SphK1 promoted cancer growth via multiple mechanisms, including S1P signaling to cancer cells." (PMID 27129720, 2016). "It is well known that SPHK-1 mediates cancer cell proliferation and progression." (PMID 27581969, 2016). "Accumulating evidences have indicated that upreguration of SphK1 could induce cancer cells resistance to apoptosis, and FTY720 has also been shown to be a potent apoptosis inducer in various cancer cells." (PMID 26673009, 2016). "In many types of cancer and in some inflammatory disease, SphK1 is overexpressed." (PMID 27129720, 2016). "We observed that 79.17% (16/24) of the cancer tissue samples showed high SphK1 expression, however, only 18.18% (4/22) of the benign group showed high SphK1 expression, the difference of SphK1 expression between ACAs and ACCs was statistically significant (P < 0.001)." (PMID 26673009, 2016). "A subsequent study proposed that ABC294640, a selective inhibitor of SphK1 that modulated the S1P level, could antagonize cancers such as breast cancer and ovarian cancer." (PMID 27129720, 2016). "Cancer studies with SphK2 are less common than those with SphK1." (PMID 27129720, 2016). "A positive correlation is known to exist between SphK1 expression and cancer progression." (PMID 26877098, 2016). "Moreover, Sphk1 overexpression correlates with a poor clinical prognosis in breast and other cancers." (PMID 27811358, 2016). "Previous studies demonstrated that inhibiting SPHK1 sensitized cancer cells to PCD in response to DNA damage, suggesting that increased S1P may protect cells from PCD in response to DNA damage." (PMID 26943039, 2016). "Our findings suggest that the reduced SIRT1 expression by tNOX knockdown was found to reduce various cancer phenotypes, and this phenomenon is similar to the way in which sphingosine kinase 1 (Sphk1) and S1P upregulate SIRT1 expression to enhance cell proliferation and migration." (PMID 27367652, 2016). "Together with our data, these observations suggest that increased SPHK1 and decreased SGPL1 or SGPP2 may be a relatively common pathogenic mechanism that could also be involved with therapy resistance in several cancer types." (PMID 26493335, 2015). "The S1P produced by SphK1 is widely appreciated as a general growth-like factor and a potent protector against apoptosis induced by cytotoxic agents and other therapies in various cancer cell and animal models." (PMID 25915662, 2015). "There are a number of SPHK1 and S1P inhibitors in clinical development as anti-cancer agents that confer increased sensitivity to cytotoxic drugs, targeted agents or radiotherapy and/or have single agent activity in preclinical cancer models." (PMID 26493335, 2015). "Despite the vast body of evidence indicating an important role for SPHK1 in cancer cell proliferation and survival, two independent research teams from industry and academia recently described selective SPHK1 inhibitors—“1a” and PF-543 —which do not affect cancer cell proliferation or survival." (PMID 24970218, 2014). "For example, SphK1 could protect cancer cells against apoptosis from apoptosis induced by TNF-a, ionizing radiation or anticancer drugs, due to increased ceramide levels." (PMID 25109605, 2014). "However, the exact role of the SPHK1 pathway, calcium channels and the NF-κB signaling network in regulating the growth of cancer cells remains to be further elucidated." (PMID 24173614, 2014). "SPHK1 is the most widely studied enzyme of sphingolipid metabolism in the context of cancer." (PMID 24970218, 2014). "Interestingly, SphK1 overexpression leading to increase S1P signaling has been demonstrated to have an important role in cancer initiation, progression and resistance to therapeutics, whereas high levels of ceramide have been reported in AD brains." (PMID 24468113, 2014). "There are a number of proposed mechanisms through which SPHK1 expression may be increased in cancers." (PMID 24970218, 2014).
cancer (continued). "The role of S1P in cancer progression has been established by studies demonstrating that the upregulation/activation of SphK1 and production of S1P inhibits apoptosis and facilitates survival of cancer cells, thus promoting tumor growth, angiogenesis, and metastasis." (PMID 24286034, 2013). "SphK1 (Sphingosine kinase 1), a master kinase that regulates the balance between ceramide/sphingosine and S1P levels, mediates cellular behaviors and may determine cancer progression, including proliferation, migration, and invasion." (PMID 24279510, 2013). "Our data provide the first evidence that cancer presence may significantly downregulate erythrocyte SphK1 activity and this significantly correlates with circulating S1P both in healthy individuals and in PCa patients." (PMID 22315056, 2012). "SphK1 has been identified as a potential therapeutic target in cancer as evidenced by two lines of investigations: (i) overexpression of Sphk1 in fibroblasts resulted in the acquisition of transformed phenotype and (ii) MCF7 cell xenografts over-expressing Sphk1 grew more rapidly in nude mice." (PMID 23028939, 2012). "However, it is still difficult to understand how such short-lived activation can be responsible for the profound involvement of SPHK1 in tumorigenicity or how this relates to its up-regulation in cancer." (PMID 21936950, 2011). "Their research finally showed that SphK1 is a convergence point of multiple cell surface receptors for three different ligands, LPA, EGF, and S1P, which have all been implicated in regulation of motility and invasiveness of cancer cells." (PMID 21936950, 2011). "Furthermore, studies have demonstrated that SPHK1 can activate the PI3K/Akt pathway in human cancers." (PMID 21625639, 2011). "Thus, SPHK1 is thought to produce the extracellular S1P that protects cancer cells from proapoptotic cytotoxics." (PMID 17024123, 2006). "Notably, targeted inhibition of SphK2 exhibits more significant anticancer effects than SphK1 in various cancer cell lines, and gene knockout experiments have confirmed that the anticancer effect of SphK2 deletion is far superior to that of SphK1 or dual enzyme inhibition." (PMID 41234914, 2025). "Furthermore, we could reveal the prognostic impact of SphK1 overproduction in the course of cancer through pan-cancer analysis using publicly accessible RNA-seq datasets from various human carcinomas." (PMID 38419070, 2024). "Additionally, the role of SPHK1 in cancer has garnered significant attention 36-37." (PMID 39629135, 2024). "Besides, SPHK1 was proven to facilitate the occurrence and development of cancer." (PMID 36823149, 2023). "Furthermore, overexpression of SphK1 has poor prognosis in patients with cancer." (PMID 36909198, 2023). "Therefore, targeting SPHK1 is likely to be a key strategy for blocking the progression of cancer." (PMID 36050478, 2022). "Moreover, numerous other cancers have high SPHK1 expression." (PMID 35965565, 2022). "SPHK1 has been shown to be significantly upregulated in a variety of cancers, such as breast cancer, lung cancer, head and neck carcinoma, and gastric cancer, which may be used as a procancer factor and therapeutic target and have an impact on diagnosis and treatment." (PMID 35126792, 2022). "Therefore, miR-mediated silencing of SphK1 could efficiently inhibit progression of various types of cancer cells." (PMID 33465049, 2021). "Additionally, our previous work showed that sphingosine 1-phosphate receptor and hyaluronan receptor cooperate to play an important role in cancer lymph-angiogenesis and lymphatic permeability, suggesting that the receptor of SPHK1 product directly interacts with the receptor of HAS2 product." (PMID 33506044, 2021).